MTOR (mechanistic target of rapamycin kinase)
Diseases named in the same sentence as MTOR in open-access papers (continued):
Sharing a sentence is not in itself a finding about the gene and the disease.
breast cancer (continued). "The mTOR inhibitor everolimus has been recently approved for the treatment of advanced ER+ breast cancer in a context of endocrine resistance." (PMID 30038706, 2018). "Aberrant activation of the PI3K/Akt/mTOR signaling pathway has been shown in numerous cancers, including breast cancers." (PMID 29523109, 2018). "ARD1 prevents mTOR activity and breast cancer cell growth by stabilizing tuberous sclerosis complex 2 (TSC2) to induce autophagy." (PMID 30154412, 2018). "Antrocin has been demonstrated to be a small-molecule inhibitor of AKT/mTOR/GSK-3β/NF-κB signaling in metastatic breast cancer cells." (PMID 30602706, 2018). "The mTOR pathway is frequently activated in TNBCs compared to other subtypes of breast cancer and is correlated with poor outcome among TNBC patients." (PMID 30248941, 2018). "Our analysis results suggest that the PI3K/AKT/mTOR inhibitors added to the therapy regimen significantly improved the PFS especially among patients with breast cancer and neuroendocrine tumours." (PMID 29408858, 2018). "Many phytochemical compounds regulate autophagy through the mTOR pathway in MCF-7 breast cancer cell models." (PMID 29587684, 2018). "The study has shown that metformin acts as a growth inhibitor in a dose-dependent manner by suppressing the mTOR/S6K pathway via LKB1–AMPK interaction in breast cancer cells, being the first to demonstrate its anticancer activity." (PMID 29805774, 2018). "In line with this, the levels of mammalian target of rapamycin (mTOR) activity and its downstream target S6 kinase were increased in LP mammary tumors." (PMID 30165877, 2018). "Metformin has been found to be an inhibitor of HKII in lung and breast cancer cell lines, primarily via inhibition of mammalian target of rapamycin (mTOR) leading to a decrease in HKII mRNA transcription." (PMID 29423101, 2018). "The PI3K/mTOR pathway is the second most frequently deregulated pathway in a majority of cancers such as breast cancer, lung cancer, and melanomas as well as leukemia." (PMID 29951132, 2018). "Molecular analysis of RTK signaling in BT474 and SKBR3 ErbB2+ breast cancer cells indicated that the combination of lapatinib with low-dose ganetespib (50 nM) enhances the inhibition of ErbB2, Akt, Erk1/2, mTOR, and GSK3 activation/phosphorylation." (PMID 29717218, 2018). "These intriguing—yet inconclusive—results point towards further single-cell resolution study of PI3K/AKT/mTOR signaling and signal activation of t-erbB2 in clinical breast cancer biopsies." (PMID 29872719, 2018). "Recently, we demonstrated that PA suppresses angiogenesis and invasion of breast cancer cells by mammalian target of rapamycin (mTOR) inhibition." (PMID 30177595, 2018). "In the present study, in addition to the mitochondrial pathway and caspases, we demonstrated that the AMPK/mTOR/4E-BP1 pathway was involved in SJWE-induced growth inhibition of MCF-7 human breast cancer cells." (PMID 29570671, 2018). "Luminal breast cancer cell lines in which the ZNF703 is overexpressed are seen to be resistant to tamoxifen through the activation of Akt/mTOR signaling." (PMID 29921827, 2018). "On the contrary, miR-99a overexpression in breast cancer cells reduced cell viability and cell apoptosis by targeting the mammalian target of rapamycin (mTOR)." (PMID 30396333, 2018). "We treated ER positive breast cancer cells with rapamycin and determined the effect of mTOR inhibition on NMT1 in a time dependent manner." (PMID 30154572, 2018). "The recent development and clinical testing of PI3K/Akt/mTOR inhibitors have led to the conclusion that targeting the PI3K/Akt/mTOR pathway is a promising approach for the treatment of breast cancer." (PMID 29523109, 2018). "Collectively, the results showed that delphinidin induced apoptosis and autophagy in HER-2 positive breast cancer cells and that autophagy was induced via the mTOR and AMPK signalling pathways." (PMID 29587684, 2018).
breast cancer (continued). "In the present study, we provide evidence that SJWE suppresses cell proliferation and induces apoptosis in MCF-7 human breast cancer cells through AMPK/mTOR and apoptotic signaling through the mitochondria." (PMID 29570671, 2018). "Various PI3K/AKT/mTOR inhibitors have been identified as promising antitumor drugs in advanced breast cancer." (PMID 29515110, 2018). "While the PI3K/AKT/mTOR pathway is known to be an important growth pathway in HR positive breast cancer, PI3K inhibitors have been disappointing due to modest effect sizes and significant toxicity." (PMID 30148117, 2018). "Additional experiments will be necessary to properly demonstrate impaired end-joining DNA repair in everolimus-treated tumors and to validate FANCD2 as a key component of the cross-talk between mTOR and DNA repair in breast cancer." (PMID 30038706, 2018). "With sustained inhibition of mTOR, breast cancer cells can take advantage of upstream RTK feedback signaling to acquire resistance to drugs." (PMID 29942710, 2018). "In line with PI3K/mTOR inhibitors, various kinase inhibitors have entered into clinical trials for gastrointestinal cancers, thyroid carcinoma, breast cancer, and endocrine tumors." (PMID 29455673, 2018). "It was shown that the Aurora kinase A inhibitor Alisertib induces cell cycle G2/M arrest and apoptosis via Akt/mTOR signaling pathways in human breast cancer cells." (PMID 29560108, 2018). "This study reported novel functions of delphinidin: the induction of apoptosis and protective autophagy in HER-2-positive MDA-MB-453 and BT474 breast cancer cells and the induction of autophagy through the modulation of the mTOR and AMPK signalling pathways." (PMID 29587684, 2018). "The deregulation of the PI3K/Akt/mTOR pathway plays a fundamental role in breast cancers, including cases of advanced TNBCs." (PMID 30248941, 2018). "For example, melittin, the major peptide component in the venom of honey bee Apis mellifera, has been shown to suppress EGF-induced cell motility and invasion by inhibiting PI3K/Akt/mTOR signaling pathway in breast cancer cells." (PMID 30400202, 2018). "In 2012, the U.S. FDA approved everolimus (RAD001) as the first PI3K/AKT/mTOR pathway inhibitor for the treatment of advanced ER+ breast cancer in combination with the steroidal AI exemestane following progression on a non-steroidal AI." (PMID 29507656, 2018). "Using loss-of-function strategies, we demonstrated that the mTOR inhibitor rapamycin and shRNA to specifically knock down mTOR gene expression in breast cancer cells dramatically prevented induction of senescence in tumor cells mediated by SALL1 expression." (PMID 29625565, 2018). "Abnormalities in the CDK4/6 and the mTOR pathways play acrucial role in the pathogenesis of breast cancer." (PMID 29162647, 2018). "Several studies, combining inhibitors of RET and mTOR signaling (e.g., everolimus) have shown increased or prolonged benefit over single agents in thyroid and breast cancer models." (PMID 30666215, 2018). "In breast cancer cell lines the positive regulation of OGT expression through mTOR is dependent on c-Myc-induced heat shock protein 90A (HSP90A) transcription." (PMID 30356686, 2018). "Aberrant activation of the PI3K/Akt/mTOR pathway is found in many types of cancer including breast cancer." (PMID 29523109, 2018). "Another druggable pathway in breast BM is the phosphatidylinositol 3 kinase/Akt/mammalian target of rapamycin (mTOR) pathway, which is dysregulated in a significant number of HR-positive breast cancers." (PMID 29881714, 2018). "Neuroblastoma and breast carcinoma models have provided evidence that mTOR activates pathways relevant to motility regulation." (PMID 30200497, 2018). "A wealth of evidence suggests an important role for the mTOR/VEGF pathway in HER2 positive breast cancer after the initial finding that rapamycin can dramatically inhibit breast tumour growth and vascularisation." (PMID 28615679, 2017).
breast cancer (continued). "The challenge now is to try new target therapies directed to AKT2-activated downstream signaling in combination with drugs that target PI3K and/or mTOR to achieve optimal efficacy in decreasing breast cancer progression." (PMID 28287129, 2017). "Zhang and colleagues reported that miR-147 inhibited breast cancer migration and proliferation by targeting the Akt/mTOR pathway." (PMID 29371970, 2017). "Previous studies reported that ERBB2 induction of the invasion and migration of breast cancer cells required activation of the small GTPases and mTOR signaling." (PMID 29089858, 2017). "In conclusion, we have recently seen significant improvements in PFS in selected breast cancer patients based on novel drug combinations involving AIs, mTOR inhibitors, HER2 directed therapies, PI3K inhibitors and CDK4/6 inhibitors." (PMID 27923036, 2017). "Diosgenin arrested the cell cycle at sub-G1 phase, suppressed FAS expression, and inhibited mammalian target of rapamycin (mTOR) phosphorylation in HER2 overexpressing human AU565 breast cancer cells, inhibiting cell proliferation." (PMID 28304343, 2017). "Mechanistically, UCA1 is thought to promote tamoxifen resistance in breast cancer cells by activating the AKT/mTOR signaling pathway, where several additional miRNAs are thought to be involved in the chemoresistance phenomenon." (PMID 29299178, 2017). "The effect of dysregulation of the mTOR signaling pathway on the survival of breast cancer patients has been reported extensively in recent years." (PMID 28114374, 2017). "Cannabidiol has previously been shown to deactivate Protein Kinase B/Akt (PKB) and mammalian Target of Rapamycin (mTOR) in breast cancer cells, so we performed a dose response over 4 h to confirm this in Jurkat cells." (PMID 28392768, 2017). "Together, these results indicated that AMPK/mTOR/Akt signaling pathway plays a crucial role in BME-induced autophagy in breast cancer cells." (PMID 29029506, 2017). "Based on the contradictory results from different studies, the aim of this meta-analysis was to assess the prognostic value of p-mTOR expression in patients with breast cancer." (PMID 28114374, 2017). "The mammalian target of rapamycin (mTOR) pathway, hyperactive in numerous cancer types including breast cancer, is an attractive therapeutic target." (PMID 28356082, 2017). "And according to the annotation result of CIViC, we found that FBXW7 deletion enhanced the sensitivity to mTOR inhibitors in breast cancer and renal cell carcinoma." (PMID 29127303, 2017). "As mTOR complex has several constitutively expressed factors in several breast cancer cell lines, the modulation of these complexes upon inflammatory signal is best studied by inducible activation of its downstream pathway." (PMID 28658303, 2017). "In the context of breast cancer, the mTOR signaling pathway has been shown to be involved in crosstalk with ERα signaling under estrogen stimulation." (PMID 28793923, 2017). "Cryptotanshinone (CPT) has been demonstrated to inhibit proliferation and mammalian target of rapamycin (mTOR) pathway in MCF‐7 breast cancer cells." (PMID 28272775, 2017). "Accordingly, A-443654 rapidly increased Akt phosphorylation, which was more pronounced in the MCF7 as compared to the MB231 cell line, and suggesting a particular responsiveness of the PI3K-Akt-mTOR pathway in ER positive breast cancer cells." (PMID 28476032, 2017). "It is known that the PI3K/AKT/(mTOR) pathway is aberrantly activated in numerous human cancers, including breast cancer." (PMID 29147947, 2017). "In breast cancer cells, mTOR inhibition by temsirolimus inhibited angiogenesis via transcriptional inhibition of VEGF production." (PMID 28615679, 2017). "This caused inhibition of mTOR following the activation of the AMPK cascade and strictly correlated with a reduced clonogenicity, migration and invasion of multiple breast cancer cell lines." (PMID 28698800, 2017).
breast cancer (continued). "The PI3K-Akt-mTOR signaling pathway, which is usually abnormal in many human cancers such as pancreatic cancer, colon cancer, breast cancer, and lung cancer, was identified as a direct target." (PMID 29212166, 2017). "In conclusion, our findings showed that TRPC5-induced autophagy counteracts the antiproliferative effects of ADM via the CaMKKβ/AMPKα/mTOR pathway in breast cancer cells." (PMID 28600513, 2017). "This gives rationale to a druggability of EEF1A2-dependent tumor growth in PCa with mTOR inhibitors, which are already in clinical use e.g. for metastatic renal cell carcinoma, breast cancer, neuroendocrine tumors and certain lymphomas." (PMID 28923030, 2017). "Intriguingly, HEK cells that were transfected either with H-rasG12V or K-rasG12V recapitulated the rapalog-induced increase in sphere numbers that was observed in breast cancer cell lines, while remaining sensitive to mTOR inhibitors." (PMID 28562352, 2017). "mTOR regulation of VEGF was suggested in human epidermal growth factor receptor 2 (HER2) positive breast cancer in response to activation of ERB2/PI3K/Akt pathway." (PMID 28615679, 2017). "Targeted therapies directed against the key members of the growth factor receptor network (GFRN), such as EGFR, PI3K, AKT, and mTOR inhibitors, are currently in preclinical development, clinical trials, or approved for use in breast cancer." (PMID 28446242, 2017). "Studies have shown that luminal breast cancer cells and basal-like breast cancer cells exploit Rictor-dependent mTOR signaling pathways to facilitate invasion and metastasis." (PMID 28666462, 2017). "We provided evidence that CCL5 activation of CCR5 can stimulate proliferation of breast cancer cells in an mTOR-dependent manner." (PMID 29216863, 2017). "There is a crosstalk between IGF‐1/mTOR pathway and ER signalling in endocrine‐resistant breast cancer." (PMID 28272775, 2017). "In an in vitro study, radiotherapy was found to induce autophagy in the MDA-MB-23 breast cancer cell line through PI3K-Akt-mTOR pathway, in which the rate of autophagy was increased to improve tumour cell survival." (PMID 28320471, 2017). "The expression of Acyl-CoA synthetase 4 (ACSL4), an enzyme participating in arachidonic acid metabolism, drives the hyperactivation of the PI3K-Akt-mTOR pathway in in vitro transfection experiments in breast cancer cells." (PMID 27765921, 2017). "Activation of mTOR/STAT3 signaling has been linked to the development and progression of cancers such as breast cancer, gastric cancer and liver cancer." (PMID 29016699, 2017). "Among these pathways, EIF2 signaling, 14-3-3-mediated pathway and mTOR signaling are particularly significant and relevant to breast cancer." (PMID 29108258, 2017). "Our findings indicate that BME-induced autophagy in breast cancer cells involves an inhibition of the mTOR pathway." (PMID 29029506, 2017). "Recent studies reported that acyl‐CoA synthetase 4 (ACSL4) also plays a mediated role in occurrence of tamoxifen resistance via interrupting mTOR signal pathway in breast cancer." (PMID 28272775, 2017). "In agreement with the previous findings that inhibition of mTOR induces autophagy, our data showed that the autophagy induced by TRPC5 is dependent on mTOR inhibition in breast cancer cells undergoing chemotherapy." (PMID 28600513, 2017). "It has been reported that UCA1 enhances tamoxifen resistance in breast cancer cells via regulating AKT/mTOR signaling pathway." (PMID 29221199, 2017). "In this study, we investigated the vertical targeting of PI3K/Akt/mTOR pathway in breast cancer cells." (PMID 28991258, 2017). "It has been previously shown that SFN inhibits Akt-mTOR survival pathway in leukemia cells and in breast cancer cells differing in growth factor receptor status." (PMID 27154770, 2017).
breast cancer (continued). "In vitro studies in canine mammary cancer cell lines show that cSrc influences these pathways and so combination therapies of cSrc and mTOR inhibitors, or direct targeting of P4 or GH signaling are therefore possible new targets for therapeutic interventions." (PMID 28451590, 2017). "In this study, we evaluated the effects of vertical inhibition of mTOR and Akt in breast cancer cell lines and xenografts." (PMID 28991258, 2017). "Based on several studies, it is thought that UCA1 either manipulates the mTOR signaling pathway and/or exploits an miR-18a-HIF1α feedback loop as well as the Wnt/β-catenin signaling pathway to confer tamoxifen resistance in breast cancer." (PMID 29299178, 2017). "For example, deep sequencing of MCF7 breast cancer cells acquiring mTOR resistance revealed the juxtaposition of the binding sites of rapamycin and AZD8055, an mTOR kinase inhibitor." (PMID 28822012, 2017). "The mTOR inhibitors have shown to improve the outcome of taxane and tamoxifen treatment in patients with advanced and ER (+)breast cancer." (PMID 29029490, 2017). "Everolimus, an mTOR inhibitor, is an immunosuppressive drug used for the treatment of breast cancer, neuroendocrine tumours, and kidney cancer; however, there has been no report on the therapeutic use of everolimus for PBL." (PMID 28860565, 2017). "PI3K/Akt/mTOR signaling pathway was shown to lead to anti-estrogen therapy resistance in cell lines of breast cancer." (PMID 29311925, 2017). "After MK-2206 and rapamycin treatment, key downstream proteins within Akt/mTOR pathway were dephosphorylated in breast cancer cell lines, including Akt, mTOR, S6 and 4E-BP1." (PMID 28991258, 2017). "In particular, cell lines made resistant to doxorubicin by continous drug exposure were compared with doxorubicin-naïve cells to decipher the role of Akt-mTOR-S6K signaling in breast cancer chemoresistance." (PMID 28476032, 2017). "Overall, CPT inhibition of mTOR is dependent on ERα in breast cancer and should be a potential anti‐oestrogen agent and a natural adjuvant for application in endocrine resistance therapy." (PMID 28272775, 2017). "c-Myc also modulates resistance to chemotherapy or mTOR inhibitors in leukemia stem cells or breast cancers." (PMID 29228674, 2017). "Raphael found that GL had a marked inhibitory role in AKT/mTOR signaling and resulted in repressed growth of breast cancer stem/progenitor cells." (PMID 28675698, 2017). "Clinical efficacy of the mTOR inhibitor everolimus is limited in breast cancer and regularly leads to side-effects including hyperglycemia." (PMID 28356082, 2017). "As one example, it has previously been shown that mTOR inhibition by everolimus in aromatase inhibitor-resistant breast cancer results in a concurrent induction of autophagy and a downregulation of the ER." (PMID 28793923, 2017). "As the PI3K/Akt/mTOR pathway is heavily deregulated in breast cancer, inhibitors of mTOR are of interest as potential therapeutic agents for breast cancer patients, with everolimus and temsirolimus being the key drugs considered." (PMID 28727815, 2017). "The pathway interaction between glutamine catabolism and mTOR activity need to be further investigated in these basal breast cancer cell lines." (PMID 28950000, 2017). "Some secoiridoids from extra virgin olive oil, i.e., oleuropein aglycone and decarboxymethyl oleuropein aglycone, have been demonstrated to activate AMPK, which results in the inhibition of the mammalian target of rapamycin (mTOR) in breast cancer cells." (PMID 28278224, 2017). "The phosphoinositol-3-kinase/serine-threonine protein kinase B/mammalian target of rapamycin (PI3K/Akt/mTOR) signalling pathway, which plays important biological roles in normal cellular physiology, has been demonstrated to be activated in breast cancer." (PMID 28060760, 2017).